ALKBH3 (alkB homolog 3, alpha-ketoglutarate dependent dioxygenase)
Diseases named in the same sentence as ALKBH3 in open-access papers (continued):
Sharing a sentence is not in itself a finding about the gene and the disease.
non-small cell lung carcinoma (5 papers, 2011 to 2025). A group of at least three distinct histological types of lung cancer, including non-small cell squamous cell carcinoma, adenocarcinoma, and large cell carcinoma. "It was also suggested that ALKBH3 contributes to cell survival in urothelial carcinoma and non-small-cell lung cancer (NSCLC) by regulating the expression of p21 and p27 which are cell cycle arrest proteins." (PMID 40483535, 2025).
lung adenocarcinoma (4 papers, 2011 to 2024). A carcinoma that arises from the lung and is characterized by the presence of malignant glandular epithelial cells. "In lung adenocarcinoma only, ALKBH3 positivity was also statistically associated with recurrence-free survival and with factors such as gender, tumour stage and degree of pleural invasion (P-factor); these associations did not hold for squamous cell carcinoma (data not shown)." (PMID 21285982, 2011). "In human lung cancers, particularly in lung adenocarcinomas and squamous cell carcinomas, ALKBH3 was overexpressed and was significantly correlated to recurrence-free survival." (PMID 37612540, 2023). "Knockdown experiments using siRNA revealed that ALKBH3 contributes to lung adenocarcinoma cell growth through accelerating G1/S transition." (PMID 21285982, 2011). "In this study, we found not only overexpression of ALKBH3 in lung adenocarcinoma cells but also a correlation between expression profile and recurrence-free survival (RFS)." (PMID 21285982, 2011). "In the human lung adenocarcinoma cell line A549 RT–PCR and western blotting data showed that ALKBH3 gene expression was significantly reduced by transfection with 100 nM siRNA (Qiagen) for 72 h." (PMID 21285982, 2011). "Knockdown of ALKBH3 by siRNA transfection induced expression of p21WAF1/Cip1 and p27Kip1 in the human lung adenocarcinoma cell line A549, resulting in cell cycle arrest, senescence and strong suppression of cell growth in vitro." (PMID 21285982, 2011). "It therefore appears that, in human lung adenocarcinoma cells, ALKBH3 knockdown inhibits cell survival, presumably through p21/p27-mediated cell cycle arrest at G1, followed by cellular senescence." (PMID 21285982, 2011). "Silencing ALKBH3 led to cell cycle arrest and senescence in vitro and peritoneal tumor growth and dissemination in vivo, possibly by inducing the expression of p21WAF1/Cip1 and p27Kip1 in lung adenocarcinoma cells." (PMID 37612540, 2023). "We suggest that ALKBH3 contributes significantly to cancer cell survival and may be a therapeutic target for human adenocarcinoma of the lung." (PMID 21285982, 2011). "As generally accepted, cancer cells arrested at G1 phase are much more sensitive to DNA damaging reagents; therefore, ALKBH3 may be one of the key molecules that determine chemotherapeutic efficacy in lung adenocarcinomas." (PMID 21285982, 2011). "On the basis of these initial results, we examined the relationship between ALKBH3 expression and selected clinicopathological parameters in 132 surgical specimens of NSCLC, comprised of 86 human lung adenocarcinomas and 46 squamous cell carcinomas, in more detail." (PMID 21285982, 2011).
ovarian carcinoma (4 papers, 2021 to 2024). A malignant neoplasm originating from the surface ovarian epithelium. "In ovarian cancer, ALKBH3 can extend the half-life of CSF-1 mRNA and enhance the expression of CSF-1 by making CSF-1mRNA near the origin of translation 5’UTR region m1A demethylation, thereby improving the invasion ability of ovarian cancer cells." (PMID 38343637, 2024). "ALKBH3 reduces m1A methylation, increases the stability of macrophage colony-stimulating factor (CSF-1) mRNA, and promotes the progression of breast and ovarian cancers." (PMID 39726589, 2024). "In breast and ovarian cancer, ALKBH3 functions as an oncogene for cancer invasiveness via stabilizing colony-stimulating factor 1 (CSF-1) transcript in an ALKBH3-mediated m1A demethylation manner." (PMID 34272618, 2021).
renal cell carcinoma (4 papers, 2021 to 2024). "ALKBH3 is highly expressed in human tumors including prostate, non-small-cell lung, pancreatic, and renal cell carcinoma, and elevated ALKBH3 expression is associated with poor prognosis." (PMID 33376192, 2021). "The expression of ALKBH3 was upregulated to varying degrees in PC, HCC, renal cell carcinoma (RCC), and urothelial carcinoma." (PMID 37007161, 2023).
cervical carcinoma (3 papers, 2016 to 2021). A carcinoma arising from either the exocervical squamous epithelium or the endocervical glandular epithelium. "Sequencing of the tsRNA in HeLa cells stably expressing ALKBH3 and control cells was applied in a study to explore the function of ALKBH3 in a cervical cancer HeLa cell line." (PMID 34907180, 2021). "This evidence indicates that 5-‘tRF-GlyGCC is involved in the progression of ALKBH3-mediated cervical cancer." (PMID 34907180, 2021).
glioma (3 papers, 2021 to 2024). A benign or malignant brain and spinal cord tumor that arises from glial cells (astrocytes, oligodendrocytes, ependymal cells). "Kaplan–Meier survival curves showed that overexpression of TRMT61B, TRMT6, TRMT61A, YTHDFs, ALKBH1, and ALKBH3 was significantly associated with poor overall survival in glioma." (PMID 34631793, 2021). "Then we found that overexpression of TRMT61B, TRMT6, TRMT61A, YTHDFs, ALKBH1, and ALKBH3 was significantly associated with poor overall survival in glioma." (PMID 34631793, 2021). "And the overexpression of ALKBH3 could inhibit glioma cells death caused by D-2-HG." (PMID 34631793, 2021).
ocular melanoma (3 papers, 2024 to 2025). A melanoma that arises from the structures of the eye or ocular adnexa. "Elevated levels of ALKBH3 in ocular melanoma correlated with reduced m1A levels and are linked to poor clinical outcomes." (PMID 40484921, 2025). "We then explored the mechanism underlying the inhibitory effect induced by ALKBH3 silencing in ocular melanoma cells." (PMID 38118002, 2024). "Bioluminescence imaging showed a weaker signal intensity in ALKBH3-deficient ocular melanoma cells than in control cells." (PMID 38118002, 2024). "Consistently, the stable knockdown of SP100A resulted in a compromised expression of PML expression in both wild-type (lanes 1 and 3) and ALKBH3-deficient ocular melanoma cells (lanes 2 and 4)." (PMID 38118002, 2024). "First, ALKBH3 is specifically upregulated in high-risk ocular melanoma due to excessive histone lactylation levels, referring to m1A hypomethylation status." (PMID 38118002, 2024). "As can be seen, ALKBH3 is critically involved in the pathogenesis of ocular melanoma, primarily through its regulation of m1A methylation." (PMID 40484921, 2025). "In this study, we revealed for the first time that global m1A modification is specifically decreased in ocular melanoma, which is attributed to the increased ALKBH3 expression by histone lactylation." (PMID 38118002, 2024). "Taken together, these experiments demonstrated that ALKBH3 plays an oncogenic role in the tumorigenesis of ocular melanoma in vitro and in vivo." (PMID 38118002, 2024). "To further verify the relationship between ALKBH3 and SP100A expression, we further altered SP100A expression after ALKBH3 inhibition in ocular melanoma cells by transfecting a reported shRNA against SP100A." (PMID 38118002, 2024). "Consistently, a dramatic genome-wide change in the proteomic levels was observed (149 upregulated and 67 downregulated proteins), further underscoring the importance of ALKBH3 in the pathogenesis of ocular melanoma." (PMID 38118002, 2024). "We then verified the expression pattern between pan-lactylation and histone lactylation marker (H3K18la) in the ocular melanoma cohorts, which showed a remarkable positive correlation with ALKBH3 protein expression." (PMID 38118002, 2024). "Since ALKBH3 is responsible for removing m1A modifications from RNA, we first performed m1A-MeRIP-seq of both ocular melanoma cells and normal melanocytes (deposited in GEO database: GSE213748)." (PMID 38118002, 2024). "Together, these results suggested that ALKBH3 promotes ocular melanoma through the decrease of SP100A-mediated PML bodies both in vivo and in vitro." (PMID 38118002, 2024). "Interestingly, the decrease in m1A modification levels was restored after ALKBH3 inhibition in ocular melanoma cells, as demonstrated by both m1A-MeRIP-seq (deposited in GEO database: GSE213748) and m1A-MeRIP-qPCR." (PMID 38118002, 2024). "Furthermore, high-throughput transcriptome sequencing further confirmed that ALKBH3 is upregulated in ocular melanoma cell lines." (PMID 38118002, 2024). "Since previous studies have indicated histone lactylation contributes to the activation of oncogenes and ocular melanoma harbor an increased lactylation level, we assume that the increase of ALKBH3 levels could be related to the histone lactylation." (PMID 38118002, 2024). "Moreover, ALKBH3 silencing resulted in significant attenuation of cell growth and colony formation capacity in all tested ocular melanoma cells." (PMID 38118002, 2024). "Moreover, elevated ALKBH3 is associated with unfavorable outcomes, further underscoring the importance of ALKBH3 in the carcinogenesis of ocular melanoma." (PMID 38118002, 2024). "However, the function of ALKBH3-mediated m1A demethylation of tRNAs/rRNAs in the oncogenesis of ocular melanoma remains enigmatic, which warrants further explorations." (PMID 38118002, 2024).
ocular melanoma (continued). "In addition, the demethylase ALKBH3 exhibited increased protein expression in tumors, which is in agreement with the finding of decreased m1A levels in ocular melanomas." (PMID 38118002, 2024). "Interestingly, combining these multiomics data, we noticed that nuclear autoantigen speckled protein 100 (SP100) was upregulated at both the mRNA and protein levels after silencing ALKBH3 in ocular melanoma cells, following a dramatic change in the m1A modification level." (PMID 38118002, 2024).
urothelial carcinoma (3 papers, 2011 to 2024). A malignant neoplasm derived from the transitional epithelium of the urinary tract (urinary bladder, ureter, urethra, or renal pelvis). "It has also demonstrated that ALKBH3 exerts the oncogenic role in the survival, angiogenesis, and invasion of urothelial carcinoma cells." (PMID 38721006, 2024). "The signaling pathways such as VEGF (pancreatic cancer), NOX-2-ROS, and Tweak/Fn12-VEGF (urothelial carcinoma) were involved in the ALKBH3 regulation." (PMID 37007161, 2023). "ALKBH2 and ALKBH3 share the ability of E.coli AlkB to directly reverse nucleic acid damage in vitro, and we reported in a recent study that ALKBH8 has important roles in the survival and progression of human urothelial carcinoma both in vitro and in vivo." (PMID 21285982, 2011).
cognitive decline (2 papers, 2024 to 2025). "Our findings further unveil that Alkbh3-deficency mice display reduced neurogenesis and cognitive decline." (PMID 39004750, 2024).
lung squamous cell carcinoma (2 papers, 2011 to 2016). "Our immunohistochemical analysis of human adenocarcinomas and squamous cell carcinomas of the lung not only showed overexpression of ALKBH3 in these tumours but the percentage of cells positive for ALKBH3 also correlated statistically to recurrence-free survival in adenocarcinoma." (PMID 21285982, 2011).
melanoma (2 papers, 2024 to 2025). A malignant, usually aggressive tumor composed of atypical, neoplastic melanocytes. "Moreover, SP100A inhibition significantly enhanced cell migration ability and compromised the inhibitory efficacy in ALKBH3-deficient melanoma cells." (PMID 38118002, 2024). "Histone lactylation disrupts tumor-suppressive nuclear bodies, increasing the expression of ALKBH3, and accelerating the development of melanoma." (PMID 39968078, 2025). "Most importantly, the knockdown of SP100A further rescued orthotopic tumor formation in ALKBH3-depleted melanoma cells." (PMID 38118002, 2024). "To assess their tumor formation ability in vivo, we injected control and ALKBH3-silenced 92.1 melanoma cells (luciferase-labeled) into nude mice and monitored tumor growth in the orthotopic xenograft model." (PMID 38118002, 2024). "Targeting ALKBH3 or changing histone lactylation may provide melanoma patients with additional therapy alternatives." (PMID 39968078, 2025). "Importantly, the silencing of ALKBH3 exhibits great therapeutic efficacy in melanoma both in vitro and in vivo, and these effects are attenuated by the depletion of SP100A." (PMID 38118002, 2024). "Therapeutically, the silencing of ALKBH3 exhibits efficient therapeutic efficacy in melanoma both in vitro and in vivo, which could be reversed by the depletion of SP100A." (PMID 38118002, 2024). "Moreover, both histone lactylation inhibitors (oxamate and 2-DG) and LDHA/B inhibition have resulted in a dramatic decreased histone lactylation levels in the promoter region of ALKBH3, which subsequently abrogates the RNA and protein levels of ALKBH3 in all tested melanoma cells." (PMID 38118002, 2024). "Consistently, in most melanoma cell lines (MUM2B, OCM1, OMM2.3, OMM1, MEL290, 92.1, CRMM1, CRMM2, CM2005.1), a significant decrease in m1A levels and the increase of ALKBH3 levels were observed when compared with normal pigmented cells (PIG1)." (PMID 38118002, 2024).
benign prostatic hyperplasia (1 paper, 2024). A non-cancerous nodular enlargement of the prostate gland. "ALKBH3 has been implicated in PrCa development as it is overexpressed in PrCa cells but not in benign prostatic hyperplasia or in normal prostate epithelium." (PMID 39516637, 2024).
breast tumors (1 paper, 2017). "This was seen in breast tumors with high cytosine methylation levels over the ALKBH3 promoter region, i.e. those showing at least 20% cytosine methylation." (PMID 28679371, 2017). "In this study, we show that the ALKBH3 gene promoter region undergoes aberrant epigenetic repression in a significant proportion of primary breast tumours." (PMID 28679371, 2017). "Firstly, this analysis demonstrates statistically significant differences in ALKBH3 mRNA expression between normal breast tissue and tumor samples wherein breast tumors generally show reduced ALKBH3 expression." (PMID 28679371, 2017). "DNA methylation analysis for the ALKBH3 promoter region was carried out by pyrosequencing (PyroMark Q24) in 265 primary breast tumours and 30 proximal normal breast tissue samples along with 8 breast-derived cell lines." (PMID 28679371, 2017). "Out of the eight breast-derived cell lines analysed with respect to ALKBH3 promoter methylation, seven were derived from breast tumors (CAMA-1, Bt-474, HCC-38, SKBr-3, MDA-MB-231, MCF-7, MDA-MB-468) and one was derived from a fibrocystic breast lesion (MCF-10A)." (PMID 28679371, 2017). "Whether the same principle can be applied with respect to the ALKBH3 gene, i.e. by inducing 3meC and 1meA in patients having developed breast tumors with ALKBH3 promoter methylation, remains to be determined." (PMID 28679371, 2017). "On the basis of the upper 99%CI for normal breast tissue samples (99%CI upper limit ~2% methylation), the incidence of ALKBH3 promoter methylation in primary breast tumors is approximately 27%, i.e. 72 out of 265 primary breast tumors show aberrant ALKBH3 promoter methylation." (PMID 28679371, 2017). "In this way, the assay was designed to reflect ALKBH3 promoter methylation status which we then applied across 303 DNA samples, i.e. 8 breast-derived cell lines, 30 normal breast tissue samples and 265 primary breast tumors." (PMID 28679371, 2017).
Cognitive impairment (1 paper, 2024). Abnormal cognition is characterized by deficits in thinking, reasoning, or remembering. "Our data also suggest targeting Alkbh3 in regulating neurogenesis as a novel therapeutic approach for neurogenesis-related cognitive impairment." (PMID 39004750, 2024). "Herein, our data show that Alkbh3-deficency mice exhibits decreased hippocampal neurogenesis and a severe deficit in spatial learning and memory, suggesting targeting Alkbh3 regulation of neurogenesis as a potential therapeutic strategy for cognitive impairment." (PMID 39004750, 2024).
colitis (1 paper, 2021). Inflammation of the colon. "Moreover, in the mice with deficiency in three DNA repair proteins (Aag−/−/Alkbh2−/−/Alkbh3−/− triple-knockout), a single cycle of DSS-induced colitis resulted in absolute lethality of these mice." (PMID 34764977, 2021).
colorectal cancer (1 paper, 2023). A primary or metastatic malignant neoplasm that affects the colon or rectum. "For the m1A eraser genes ALKBH1 and ALKBH3, it was suggested that the mRNA expression of MFAP2 and the methylation modification of m1A were increased in colorectal cancer when ALKBH1 was silenced." (PMID 37178414, 2023).
fibrosarcoma (1 paper, 2015). A malignant mesenchymal fibroblastic neoplasm affecting the soft tissue and bone. "Notably, HT1080 cells are fibrosarcoma cells, but despite the different origin of PC3 and HT1080 cells, we still see this correlation of ALKBH3 and XPB binding." (PMID 26221185, 2015).
gastric tumour (1 paper, 2024). "Furthermore, we carefully analyzed the association of PUS7 and ALKBH3 expression in gastric tumour tissues and found a significant correlation between PUS7 and ALKBH3 levels in gastric tumour tissues in both cohorts." (PMID 39175405, 2024). "Crucially, PUS7 modifies ALKBH3 mRNA with pseudouridine (Ψ), enhancing its translation efficiency and consequently suppressing gastric tumour growth." (PMID 39175405, 2024). "Mechanistically, PUS7 catalyzes the pseudouridylation of ALKBH3 mRNA on the U696 site to enhance its translation efficiency and increase its protein levels, leading to the suppression of gastric tumour growth." (PMID 39175405, 2024). "Further studies are needed to determine which role of ALKBH3 is responsible for its regulatory effect on gastric tumour growth." (PMID 39175405, 2024). "Mechanically, PUS7 modifies ALKBH3 mRNA with Ψ, increasing its translation efficiency and thereby suppressing gastric tumour growth." (PMID 39175405, 2024). "Our study provides compelling evidence that both PUS7 and ALKBH3 are significantly and coordinately reduced in gastric tumour tissues, demonstrating their tumour‐suppressive function in gastric carcinogenesis." (PMID 39175405, 2024). "Collectively, these findings indicate that PUS7 inhibits gastric tumour growth via ALKBH3." (PMID 39175405, 2024). "Moreover, ALKBH3 overexpression suppressed the growth of gastric tumours in a xenograft mouse model." (PMID 39175405, 2024). "Given that PUS7 suppresses gastric tumour growth and pseudouridylates ALKBH3 mRNA, it is reasonable to hypothesize that ALKBH3 may be involved in the regulation of PUS7 in gastric carcinogenesis." (PMID 39175405, 2024). "To evaluate the clinical association of PUS7 with ALKBH3 expression, we first examined the levels of ALKBH3 protein in human gastric tumour tissues and their paired non‐tumour tissues." (PMID 39175405, 2024).
head and neck cancer (1 paper, 2021). A primary or metastatic malignant neoplasm affecting the head and neck. "It was found that head and neck cancer samples with high expression of writer genes KIAA1429 were in positive correlation with eraser genes ALKBH3 and FTO, while tumors with a high expression of writer genes (RBM15, RBM15B, and CBLL1) exhibited a low expression of eraser genes (ALKBH3 and FTO)." (PMID 35198565, 2021).
lymph node metastasis (1 paper, 2021). "At the same time, the mRNA expression levels of ALKBH2, ALKBH3, and ALKBH6 had a trend to upper expression in tumors with lymph node metastasis, although this was not significant." (PMID 34150745, 2021).